SNORD114-25 (small nucleolar RNA, C/D box 114-25)
Synonyms: 14q(II-25)
Gene: Small nucleolar RNA gene on chromosome 14 (100,986,057 to 100,986,128, forward strand). Ensembl gene ENSG00000200612.
Gene Ontology:
Biological process: RNA processing
Cellular component: nucleolus
Homologues: Orthologues: chimpanzee SNORD114-25 (100% identical), macaque SNORD114-25 (99% identical). Paralogues in human: SNORD114-28 (94% identical), SNORD114-22 (90% identical), SNORD114-23 (90% identical), SNORD114-9 (90% identical), SNORD114-20 (89% identical), SNORD114-21 (89% identical), SNORD114-15 (88% identical), SNORD114-26 (88% identical), SNORD114-5 (88% identical), SNORD114-29 (85% identical), SNORD114-14 (83% identical), SNORD114-3 (83% identical), and 26 more.